SLC2A1 (solute carrier family 2 member 1)
Diseases named in the same sentence as SLC2A1 in open-access papers (continued):
Sharing a sentence is not in itself a finding about the gene and the disease.
Sepsis (20 papers, 2021 to 2025). Sepsis is defined as life-threatening organ dysfunction caused by a dysregulated host response to infection. "Notably, these DEPs including Fads2, Fgb, Cypla2, Cyp2e1, Cfb, Serping1, Fgg, Etnppl, Agt, Hsd3b5, Gnmt, A2m, Pck1, Stat3, Ptpn1, Scd1, Slc2a1, and Uox were key genes in liver sepsis, which maybe associated with inflammation in sepsis." (PMID 37255592, 2023). "Gene expression of fatty acid transporters and of the glucose transporter Slc2a1 was upregulated in prolonged sepsis (p ≤ 0.01)." (PMID 39821755, 2025). "Likewise, exosomes derived from the blood of patients with sepsis can promote apoptosis in myocardial cells via the hsa‐miR‐1262/solute carrier family 2 member 1 (SLC2A1) axis." (PMID 40264381, 2025). "In sepsis, serum exosomes from patients with SIMD can target the transcription of glucose transporter GLUT1 (SLC2A1) in cardiomyocytes through miR-1262, inhibiting mitochondrial glycolysis rate and promoting cardiomyocyte apoptosis, ultimately aggravating myocardial injury." (PMID 40041174, 2025). "The boxplot revealed 26 differentially expressed genes between the sepsis-induced ALI and control samples: Ncf2, Slc2a6, Cd44, Txnip, Slc2a1, Ubc, Hspb1, Zfp36, Arntl, Ddit4, Tnfaip3, Txnrd1, Mt1, Hmox1, Gch1, Gclc, Stat3, Egfr, Hif1a, Bach1, Socs1, Dusp1, Cdkn1a, Fth1, Steap3, and Alox12." (PMID 37081490, 2023). "We performed feature selection analysis and found that combination of three genes (TLCD4, PRSS30P, and ZNF493) and seven genes (TLCD4, PRSS30P, ZNF493, AGO2, SLC37A3, SLC2A1, and RPL11) showed moderate performance in identifying patients with sepsis and ARDS within 1 day after admission." (PMID 33818300, 2021). "Gene expression of glucose transporter GLUT1 (Slc2a1), but not GLUT4 (Slc2a4), was upregulated in acute and prolonged sepsis." (PMID 39821755, 2025).
endometrial cancer (19 papers, 2009 to 2025). Primary or metastatic malignant neoplasm involving the endometrium (mucous membrane that lines the endometrial cavity). "Our pathway analysis in endometrial cancer (EC) reveals SLC2A1’s involvement in diverse metabolic networks, suggesting its crucial role in tumor-specific metabolic reprogramming." (PMID 40746529, 2025). "In this study, we have firmly established the diagnostic and prognostic significance of SLC2A1 and MPST in Uterine Corpus Endometrial Carcinoma (UCEC)." (PMID 40746529, 2025). "We conducted an investigation of the SLC2A1 and MPST genes using 549 Uterine Corpus Endometrial Carcinoma (UCEC) samples with mutations." (PMID 40746529, 2025). "Both SLC2A1 and MPST showed high expression in endometrial cancer clinical samples and in the TCGA database." (PMID 40746529, 2025). "Following the database analysis, we used quantitative Polymerase Chain Reaction (qPCR) to measure the expression levels of SLC2A1 and MPST in tissue samples from patients with Uterine Corpus Endometrial Carcinoma (UCEC)." (PMID 40746529, 2025). "To better understand the significance and mechanisms of SLC2A1 and MPST expression in Uterine Corpus Endometrial Carcinoma (UCEC), we investigated the relationship between the expression levels of these proteins and various clinical features." (PMID 40746529, 2025). "Amplification of the SLC2A1 gene was found in 4% (3/76) of endometrial cancer cases, but in none of normal tissue." (PMID 22270867, 2012). "Through our analysis of the TCGA dataset, we discovered that in Uterine Corpus Endometrial Carcinoma (UCEC) samples, the expression level of SLC2A1 was negatively correlated with the expression levels of CD96, CTLA-4, and PDCD-1." (PMID 40746529, 2025).
head and neck squamous cell carcinoma (19 papers, 2010 to 2025). A squamous cell carcinoma that arises from any of the following anatomic sites: lip and oral cavity, nasal cavity, paranasal sinuses, pharynx, larynx, and salivary glands. "Meanwhile, in head and neck squamous cell carcinoma (HNSCC), the expression levels of PGK1 and SLC2A1 were upregulated and were significantly associated with the patients’ poorer overall survival (OS), disease-free survival (DFS) and relapse-free survival (RFS)." (PMID 40821990, 2025). "To gain a possible clinical connection of GLUT1 (encoded by the SLC2A1 gene) and PKM2 (encoded by the PKM2 gene) to OSCC, we assessed both gene expression in the head and neck squamous cell carcinoma (HNSCC) database of the Cancer Genome Atlas (TCGA) project through the UALCAN web portal." (PMID 36611972, 2023). "One study in head and neck squamous cell carcinoma cells demonstrated that miR-375 silenced the expression of the glucose transporter protein solute carrier family 2 member 1 (SCL2A1 or glucose transporter type 1; GLUT1) by targeting SCL2A1 mRNA." (PMID 34361112, 2021).
head and neck cancer (17 papers, 2010 to 2024). A primary or metastatic malignant neoplasm affecting the head and neck. "Subsequent analysis in head and neck cancer cells revealed down-regulation of key glycolysis genes SLC2A1 (Glut-1), PFKP, LDHA, PKM and PDK3, and reduction in pyruvate and lactate levels and glycolysis rates following treatment with the extract." (PMID 32726914, 2020). "As tumor hypoxia is the largest determinant in treatment-efficacy variability in survival in head and neck cancers many endogenous markers such as HIF1A/HIF1α, CA9/CAIX, SLC2A1/GLUT1, have been investigated." (PMID 34904929, 2022). "As tumor hypoxia is the largest determinant in treatment-efficacy variability in survival in head and neck cancers many endogenous markers such as HIF1A, CA9, SLC2A1 and others, have been investigated." (PMID 34904929, 2022).
oral cancer (17 papers, 2015 to 2025). "Treatment with BME on oral cancer cell lines significantly reduced mRNA and protein expression levels of key glycolytic genes SLC2A1 (GLUT-1), PFKP, LDHA, PKM and PDK3." (PMID 31638999, 2019). "In oral cancer, KRT17 stimulates the Akt/mTOR pathway and upregulates SLC2A1 and glucose uptake which facilitates tumor growth." (PMID 30214686, 2018).
neuroblastoma (15 papers, 2021 to 2024). Neuroblastoma (NB) is the most common solid, extracranial childhood tumor. "In patients with Wilms’ tumor and neuroblastoma, high SLC2A1 expression is correlated with unfavorable histology and high-risk features." (PMID 33810575, 2021). "Similarly, HNF4α has been shown to promote glycolysis, glucose uptake, lactic acid production and ATP levels in neuroblastoma cells, and the underlying mechanism involved hexokinase 2 (HK2) and Solute Carrier Family 2 Member 1 (SLC2A1) and the heterogeneous nuclear ribonucleoprotein U (hnRNPU)." (PMID 36249028, 2022). "In another study, it was reported that hepatocyte nuclear factor 4 alpha (HNF4A) and its derived long-noncoding RNA (HNF4A-AS1) promote aerobic glycolysis in neuroblastoma cells by upregulating HK2 and the major glucose transporter SLC2A1 (also known as GLUT1)." (PMID 36077650, 2022).
atherosclerosis (14 papers, 2018 to 2026). A disease characterized by the build-up of fatty material and calcium deposition in the arterial wall resulting in partial or complete occlusion of the arterial lumen. "Rescue of the impaired glycolysis in Prkaa1-deficient endothelial cells through Slc2a1 overexpression enhances endothelial cell viability and integrity of the endothelial cell barrier, and reverses susceptibility to atherosclerosis." (PMID 30405100, 2018). "In neutrophils, the increased uptake of glucose uptake via GLUT enhanced glycolysis in these cells, thereby triggering the production of RAGE ligand S100A8/A9, which was linked directly to atherosclerosis through myeloid-specific deletion of Slc2a1 (GLUT1)." (PMID 34178389, 2021). "To examine the role of endothelial Ad-Slc2a1 transduction in the development of atherosclerosis, we designed a model of local viral delivery to the mouse carotid endothelium." (PMID 30405100, 2018). "The effect of Prkaa1 deletion on plasma cholesterol levels, circulating monocytes and others may be important in atherosclerosis, although the Slc2a1 rescue experiment has assessed the effects of PRKAA1-driven glycolysis." (PMID 30405100, 2018). "Myeloid‐restricted Slc2a1 (GLUT1) deletion or pharmacological S100A8/S100A9 inhibition attenuated TIH‐induced myelopoiesis and atherosclerosis." (PMID 41489606, 2026). "Myeloid‐restricted deletion of Slc2a1 (GLUT1) or pharmacological inhibition of S100A8/S100A9 reduced TIH‐induced myelopoiesis and atherosclerosis." (PMID 37779347, 2023).
Hyperinsulinemia (14 papers, 2012 to 2024). An increased concentration of insulin in the blood. "The control of SLC2A1 by ENTR1 in the context of the equine athlete is intriguing to speculate since SLC2A1 is expressed within equine lamellar tissue, and its expression is increased in hyperinsulinemia, therefore may play a role in the pathophysiology of equine laminitis." (PMID 31850069, 2019).
osteoarthritis (14 papers, 2009 to 2025). A noninflammatory degenerative joint disease occurring chiefly in older persons, characterized by degeneration of the articular cartilage, hypertrophy of bone at the margins and changes in the synovial membrane. "Finally, downregulation of SLC2A1 expression by Adeno‐associated Virus (AAV) ‐SLC2A1 shRNA improves osteoarthritis in vivo." (PMID 36890785, 2023). "For example, capsiate inhibited the expression of HIF-1α by activating SLC2A1, thereby reducing the progression of ferroptosis-related osteoarthritis." (PMID 40809843, 2025). "A different research study found that has reported that the activation of lncRNA SLC2A1 declined the expression of HIF-1α to inhibit osteoarthritis." (PMID 38740637, 2024). "Our findings indicated that CAT inhibited HIF‐1a expression and reduced ferroptosis‐relative osteoarthritis progression by activating SLC2A1." (PMID 36890785, 2023). "Our findings indicated that CAT inhibited HIF‐1a expression and reduced ferroptosis‐dependent osteoarthritis progression by activating SLC2A1." (PMID 36890785, 2023). "Also, we found that CAT inhibited HIF‐1a expression and reduced ferroptosis‐dependent osteoarthritis progression by activating SLC2A1." (PMID 36890785, 2023). "SLC2A1 is also differentially expressed in response to hypoxia, this has also been shown in equine chondrocytes in vitro after exposure to cobalt chloride (to mimic hypoxia) and in chondrocytes from osteoarthritis cases." (PMID 31850069, 2019). "However, the protective effect of CAT against ferroptosis‐dependent osteoarthritis could be eliminated by silencing SLC2A1." (PMID 36890785, 2023). "To our knowledge, we are the first to report that the protective effect of CAT against osteoarthritis is mediated by the inhibition of HIF‐1 α and activation of SLC2A1, thereby inhibiting ferroptosis progression." (PMID 36890785, 2023). "Due to lipid peroxidation being an important part of ferroptosis, we used primary chondrocytes from osteoarthritis patients to analyze the role of SLC2A1 and HIF‐1α in the progression of osteoarthritis." (PMID 36890785, 2023). "Finally, to clarify the effect of SLC2A1 on the onset and progression of osteoarthritis treatment with CAT, 8‐week‐old mice were injected intra‐articularly with AVV‐specific expression of SLC2A1‐specific shRNA." (PMID 36890785, 2023). "In addition, we further investigated the possibile mechanism of HIF‐1a expression and SLC2A1 which effect by gut microbiota metabolite CAT and provide a theoretical basis for CAT treatment of osteoarthritis." (PMID 36890785, 2023).
adenoma (13 papers, 2002 to 2024). A neoplasm arising from the epithelium. "For example, while the expression of SLC2A1 (GLUT-1) is higher in ACC than in NAG and adenomas and highest in the ACC-UMAP2 cluster, the expression of MYC for example is significantly lower in both ACC clusters when compared to the NAG." (PMID 34572898, 2021). "Finally, as observed with the mouse IKKαKO large adenomas, two selected direct HIF-1α target genes (Slc2a1 and PDK1) were also found to be up-regulated by quantitative qRT-PCR in independent IKKαKD H1437 tumor xenografts." (PMID 31792060, 2019).
diabetic nephropathy (13 papers, 2010 to 2025). "We also performed a meta-analysis of 11 studies investigating association between diabetic nephropathy (DN) and SLC2A1 variants." (PMID 30353771, 2018). "Along with our findings, these reports clearly implicate a modulating role for SLC2A1 variants in diabetic nephropathy." (PMID 30353771, 2018). "For SLC2A1 SNP rs841853 and diabetic nephropathy, a similar inconsistent association result across large study populations was reported." (PMID 22509097, 2012). "The results suggest that SLC2A1 variants and haplotypes may be involved in the pathogenesis of diabetic nephropathy." (PMID 30353771, 2018). "However, since the sample size of the present association study was relatively small, we performed a meta-analysis considering all published studies, which investigated the association between SLC2A1 variants and diabetic nephropathy." (PMID 30353771, 2018). "However, additional studies and a genetic convergence analysis of different data sources are needed in order to merit prioritization in future studies producing more conclusive claims of the association between SLC2A1 and genetic susceptibility to diabetic nephropathy." (PMID 30353771, 2018). "Variants in SLC2A1 have been associated with diabetic retinopathy, type 2 (non-insulin-dependent) diabetes, diabetic nephropathy, and clear-cell renal cell carcinoma." (PMID 22509097, 2012).
idiopathic pulmonary fibrosis (13 papers, 2017 to 2026). Idiopathic pulmonary fibrosis (IPF) is a nonneoplastic pulmonary disease that is characterized by the formation of scar tissue within the lungs in the absence of any known cause. "Recently, Slc2a1-ΔM mice were studied in a S. pneumoniae infection model superimposed on bleomycin-induced lung fibrosis." (PMID 41226500, 2025). "S. pneumoniae infection exacerbated lung fibrosis, which was mitigated in Slc2a1-ΔM mice, suggesting that GLUT1-dependent glycolysis regulates the worsening of fibrosis in response to S. pneumoniae infection." (PMID 41226500, 2025).
lung squamous cell carcinoma (13 papers, 2019 to 2025). "In patients with lung squamous cell carcinoma, solute carrier family 2 member 1 (SLC2A1), encoding glucose transporter-1 (GLUT1), was highly expressed in SPP1+ macrophages." (PMID 39026681, 2024). "The expression of solute carrier family two member 1 (SLC2A1), which encodes the GLUT1 protein, is different between lung squamous cell carcinoma (LUSC) tissues and normal lung tissues." (PMID 40584966, 2025).
metastatic tumors (13 papers, 2010 to 2025). "Specifically, the proportion of SLC2A1 high-expressing cells was greater in metastatic tumors, reflecting the gene’s important role in the metastatic process." (PMID 39992528, 2025). "Through population proportion analysis, we observed a significant difference in the proportions of epithelial cells expressing high versus low levels of SLC2A1 in primary versus metastatic tumors." (PMID 39992528, 2025). "We analyzed SLC2A1 expression among normal and primary tumor or metastatic tumor paired (matched) samples." (PMID 33735188, 2021). "On the other hand, SLC2A1 expression was higher in metastatic cancers than in primary cancers (58 primary tumor versus 58 metastatic tumor samples, p = 0.299) (left)." (PMID 33735188, 2021). "In metastatic tumors, pathway and TF analyses revealed strong hypoxia-inducible factor-1α–driven hypoxia activation, influencing glycolysis (SLC2A1, SLC2A3, PGK1, PDK1, PGM1, and ALDOA), angiogenesis (ANGPTL4 and ADM), and survival in low oxygen (BNIP3, BNIP3L, and NDRG1)." (PMID 40736012, 2025). "SLC2A1 was more highly expressed in metastatic tumors than in primary tumors." (PMID 33735188, 2021).
myeloma (13 papers, 2014 to 2024). "The glucose transporter GLUT1, encoded by the gene Slc2a1, is highly expressed by multiple myeloma cells, which are transformed counterparts of long-lived plasma cells." (PMID 36001583, 2022). "Of the 13 members of the Slc2 family in mice, primary plasma cells and/or myeloma cells expressed SLC2A3, SLC2A6, and SLC2A8 as candidate glucose transporters in addition to SLC2A1." (PMID 36001583, 2022).
rectal cancer (13 papers, 2003 to 2023). A primary or metastatic malignant neoplasm that affects the rectum. "To further evaluate the association between the expression of SLC2A1 and rectal cancer, we performed a subgroup analysis for rectal cancer patients using a univariate Cox regression analysis." (PMID 30943948, 2019). "Although we were unable to confirm our findings in the validation set due to a lack of primary site information, in the discovery set, SLC2A1 expression in rectal cancer patients (n = 72) was significantly associated with DFS (HR 1.57, 95% CI: 1.04–2.38; P = 0.03)." (PMID 30943948, 2019).
renal carcinoma (13 papers, 2016 to 2025). A carcinoma arising from the epithelium of the renal parenchyma or the renal pelvis. "At the molecular level, we found that SLC2A1, LDHA, GOT1, and GOT2 were regulated by HGD and GSTZ1 to alter the glucose uptake and energy metabolism of renal cancer cells." (PMID 35562974, 2022).
invasive breast carcinoma (12 papers, 2009 to 2022). A carcinoma that infiltrates the breast parenchyma. "The Curtis Breast dataset indicated that compared to normal samples, SLC2A1 overexpression is also found in medullary breast carcinoma (fold change = 2.728), in mucinous breast carcinoma (fold change = 2.100) and in invasive breast carcinoma (fold change = 2.317)." (PMID 34525987, 2021). "However, in Finak’s datasets, SLC2A1 was significantly down-regulated in invasive breast carcinoma stroma sample with a 3.780-fold change." (PMID 34488531, 2021). "The results showed that the expression level of SLC2A1 were higher in breast invasive carcinoma than in pairing normal tissues, and the expression levels of SLC2A3 and SLC2A4 were significantly lower in breast invasive carcinoma than in pairing normal tissues." (PMID 34525987, 2021).
pancreatic adenocarcinoma (11 papers, 2012 to 2025). "Specifically, elevated SLC2A1 expression is associated with poor overall survival in pancreatic adenocarcinoma, where it promotes cell proliferation, invasion, and metastasis." (PMID 39858431, 2024).
paroxysmal dyskinesia (11 papers, 2013 to 2025). Paroxysmal dyskinesia (PD) is a rare heterogenous group of movement disorders manifesting as abnormal involuntary movements that recur episodically and last only a brief time. "Fourteen SLC2A1 mutations were identified in the paroxysmal dyskinesia series (10%) and one in the episodic ataxia and familial hemiplegic migraine series." (PMID 26598494, 2015). "In earlier reports, most patients carried mutations in paroxysmal dyskinesia-specific genes such as PRRT2, PNKD and SLC2A1, typically associated with isolated phenotypes and favourable treatment responses." (PMID 40943684, 2025).
sarcoma (11 papers, 2012 to 2025). A usually aggressive malignant neoplasm of the soft tissue or bone. "Considering pediatric sarcomas, our team previously reported that abundance of hypoxic markers (specifically SLC2A1 and CA9) in rhabdomyosarcoma characterized aggressive tumors resistant to neoadjuvant chemotherapy." (PMID 33810575, 2021).
Doose syndrome (10 papers, 2017 to 2025). "Here, we report a case of myoclonic-atonic epilepsy (MAE) caused by a novel de novo mutation in SLC2A1 gene." (PMID 31045803, 2019). "Based on recent reports describing SLC2A1 mutations in patients with myoclonic astatic epilepsy (MAE), early onset absence epilepsy (EOAE), and genetic generalized epilepsies (GGEs), they aimed to replicate these findings in a cohort of European patients." (PMID 28507422, 2017).